IL6 (interleukin 6)
Diseases named in the same sentence as IL6 in open-access papers (continued):
Sharing a sentence is not in itself a finding about the gene and the disease.
tumor (continued). "Abundant in the tumor microenvironment, IL-6 is involved in DNA damage repair and cancer-related inflammation." (PMID 39201656, 2024). "In IL-6+gp130+, IL-6+JAK2+, and IL-6+gp130+JAK2+ cells, the expression of IL-6 was lower in tumor tissues compared with normal tissues (P < 0.05), while the expression of JAK2 and gp130 was comparable (P > 0.05)." (PMID 38881895, 2024). "The suppression of IL-6 from mesothelial cells reduced the sphere growth advantage of Jag2OE tumor cells." (PMID 38575576, 2024). "The expression of angiogenic factors (e.g., Angiopoetinn-1, FGF acidic), chemokines (e.g., CCL2, CXCL13), and inflammatory cytokines (e.g., IL-6, IL-1 beta), which were elevated in serum from tumor embedded mice, was suppressed by Pn-21Ab administration." (PMID 39334860, 2024). "A single-cell transcriptomic study of oral squamous cell carcinoma has revealed an enrichment of the IL-6/JAK2/STAT3 axis in the tumor microenvironment, particularly in cell populations like macrophages, in samples induced by chemotherapy and other treatments." (PMID 38650924, 2024). "These probiotics have also been shown to modulate pro-inflammatory cytokines such as IL-6 and decrease tumor volume and metastasis in experimental mice." (PMID 39767682, 2024). "The engineered macrophages (LAMΦ-m7/8a) phagocytosed 4T1 tumor cells in vitro and expressed high levels of IL-6 and TNFa for 48 h in vitro." (PMID 39516356, 2024). "During tumor development, MDSCs are recruited to the tumor site by chemokines, where they induce tumor promotion by expressing IL-6 and suppressing T- and NK-cell activation." (PMID 39338937, 2024). "Patients with previous history of other neoplasms tended to present with increased circulating IL-6 levels ((median 3.2 pg/mL (IQR 74.3) vs. 0 pg/mL (IQR 2.90), p = 0.06)." (PMID 38892006, 2024). "Many studies have shown that STAT3 activation in tumor cells governs the secretion of diverse pro-inflammatory factors including IL-6, IL-10 and VEGF." (PMID 38245798, 2024). "We also found increased IL‐6 levels in the tumor homogenate from the subcutaneous model injected with Huccc9810 cells pretreated with E. coli and in the co‐culture medium derived from ICC cells indirectly co‐cultured with E. coli." (PMID 38368261, 2024). "In HNSCC, an increase in MDSCs can upregulate inflammatory mediators like IL-1 and IL-6, creating an environment unfavorable for the maturation of APCs, thereby indirectly promoting tumor cell proliferation." (PMID 38294629, 2024). "IL-6 silencing in NPC cells significantly impaired cell growth and proliferation, while exogenous IL-6 restored the malignant features of the SPZ1-knockdown NPC cells, indicating that IL-6 participates in SPZ1-mediated tumor progression." (PMID 39440046, 2024). "Treated mice showed significantly lowered tumor burdens, as well as substantial increases in IL-6 and IFN-γ." (PMID 39030582, 2024). "IL-6 expression was found in tumor cells and tumor-infiltrating leukocytes, indicating the presence of a paracrine stimulation loop." (PMID 39099925, 2024). "Among them, TNF‐α and IL‐2 are produced by Th1 cells and mediate anti‐tumour effects, while Th2 cells produce IL‐6 and IL‐10 and promote tumour growth by suppressing the immune system." (PMID 38451046, 2024). "This activation, in turn, triggers the secretion of cytokines such as IL-6 and TNFα, supporting the proliferation of tumor cells and formation of lung metastases." (PMID 38331871, 2024). "These vCAFs were shown to secrete IL-6, which induced significant epigenetic alterations in tumor cells and furthered malignancy." (PMID 38279300, 2024). "The signaling pathway is also critical in regulating the immune response in the tumor microenvironment, promoting macrophage recruitment and the transcription of IL-6 and IL-8 while suppressing the cytotoxic functions of T lymphocytes and NK cells." (PMID 38359031, 2024).
tumor (continued). "The first is that while IL-6 can lead to the activation of STAT3 in the tumor microenvironment, many other cytokines and growth factors can do so as well." (PMID 38611065, 2024). "Melatonin prevents migration and invasion in this tumor cell line by blocking the EMT activation mediated by the IL-6/STAT3, AKT/GSK-3β and β-catenin pathways." (PMID 38473317, 2024). "Interleukin-6 (IL-6), derived from cancer-associated fibroblasts (CAFs), plays a crucial role in initiating the activation of the STAT3 pathway in tumor-infiltrating neutrophils, known as TANs." (PMID 39420203, 2024). "PERK-mediated upregulation of vascular endothelial growth factor (VEGF), fibroblast growth factor-2 (FGF2), and interleukin-6 (IL-6), coupled with the downregulation of anti-angiogenic cytokines, markedly promotes tumor growth." (PMID 38673794, 2024). "Researchers in the scientific community have documented that IL-6 plays a crucial role as a driver of tumor progression and can also act as a biomarker for diagnosing and predicting the prognosis of cancer." (PMID 39770330, 2024). "In all patients with an IL-6 serum level below 5.0 pg/mL in C2, tumour regression TRG1a/1b according to the Becker classification was detected in postoperative histopathological specimens." (PMID 38398148, 2024). "In human glioblastoma, the deletion of IL-6 leads to cellular apoptosis and tumor growth resistance." (PMID 39201332, 2024). "Pro-inflammatory interleukins, such as IL-1, IL-6, and IL-8, have been identified as key drivers in promoting osteoclastogenesis, tumor proliferation, and angiogenesis." (PMID 39125732, 2024). "Of note, injection of the anti-IL-6 neutralizing antibody led to a reduction in tumor volume and weight." (PMID 38459511, 2024). "Within TME, IL-6 and its family members promote tumor cell proliferation, survival, and angiogenesis by activating signaling pathways such as JAK/STAT, PI3K/AKT, and MAPK." (PMID 39421736, 2024). "In TDLN, dendritic cells activating tumor-specific T-cells have been shown to be subjected to tumor-derived factors like IL-6, TGF-β, prostaglandin-E2, and VEGF." (PMID 38954023, 2024). "Several cytokines produced by macrophages, such as interleukin‐6 (IL‐6) and cyclooxygenase‐2 (COX‐2), have been implicated in the activation of both pro‐survival and anti‐apoptotic pathways in tumor cells and mediating resistance to chemotherapeutic drugs." (PMID 38426622, 2024). "Decreasing WAT browning by silencing tumor production of IL-6 ameliorated severity of cachexia, highlighting a new role of PTHrP and IL-6 in hypermetabolism mediated malignancy." (PMID 39273055, 2024). "The high expression of Interleukin (IL)-6 is closely related to tumor development and lymph node metastasis in patients with HNSCC." (PMID 38313306, 2024). "For example, the pro-inflammatory factors TNF-α, IL-6, and IL-1β promote tumor growth, invasion, and metastasis." (PMID 38368407, 2024). "Cancer‐associated fibroblasts (CAF) have been linked to interleukin‐6 (IL‐6) and VEGF expression and subsequent tumour angiogenesis in tumoroid co‐cultures." (PMID 39169896, 2024). "Among them, dysregulation of IL-6 signaling usually plays a core role in the differentiation of HNSCC tumor cells." (PMID 38920620, 2024). "MMPs (especially MMP9) stimulate tumor cell proliferation and the production of VEGF and subsequent angiogenesis, while IL-6, IL-1β, and TNF-α, among pro-inflammatory cytokines, support chronic inflammation preceding or associated with tumor." (PMID 38612841, 2024). "Proteins that increase JAG1 in the tumor microenvironment are proinflammatory cytokines, including IL-6." (PMID 39408921, 2024).
tumor (continued). "Recently, much attention has been given to the pleiotropic cytokine IL-6 because of its ability to either promote or, more rarely, inhibit tumor growth." (PMID 38715108, 2024). "IL-6 is involved in the proliferation and differentiation of various malignant tumor cells through the IL-6-Jak-Stat signaling pathway." (PMID 38339365, 2024). "The results suggest that AQP3 plays a key role in tumor development by mediating M2 polarization and IL-6 secretion." (PMID 39060229, 2024). "Oncoproteins also upregulate interleukin-6 (IL-6) that promotes Mcl-1, through phosphatidylinositol-3-OH kinase (P13K), thereby increasing tumor malignancy." (PMID 38255725, 2024). "Our findings reveal a significant increase in the levels of TNF-α, IFN-γ, and IL-6 in tumor tissue following treatment with AgNPs-G." (PMID 39126001, 2024). "Specifically, within the tumor microenvironment, Fg γ390-396A’s interaction with leukocyte integrin αMβ2 not only enhances the secretion of pro-inflammatory cytokines like IL-6, IL-1β, IFN-γ, and TNF-α but also promotes tumor cell proliferation." (PMID 38779081, 2024). "It was concluded that the tumor biological effects of IL-6/STAT3 signaling were similar between the PDAC subtypes, but differed strongly between the sexes, especially with regard to T cell populations." (PMID 39684385, 2024). "The secretion of cytokines such as IL-6 and IL-8 induces neutrophil recruitment to the tumor site and has pro-inflammatory and angiogenic effects." (PMID 38347528, 2024). "It is also reported that tumor-derived succinate promoted tumor-associated macrophage (TAM) polarization and IL-6 release via SUCNR1, resulting in cancer metastasis." (PMID 38291510, 2024). "IL-6 is frequently detected in high concentrations in cancer patients’ blood, tissues, and tumor mass." (PMID 39251966, 2024). "In conclusion, ENO1 promotes tumor cell migration and invasion by orchestrating macrophage-derived IL-6 via secretion of lactic acid and extracellular ENO1, thus forming a positive feedback loop to promote OSCC progression." (PMID 36614179, 2023). "There is increasing evidence that links IL-6/STAT3 to the functional properties of the cells thatform the tumor microenvironment." (PMID 37720284, 2023). "A previous study has revealed that chemotherapy-resistant HCC, such as 5-FU, increases MDSC activity, and that the use of the anti-IL-6 neutralizing antibody in combination with 5-FU significantly reduces tumor growth and can help overcome drug resistance." (PMID 36769116, 2023). "In constant, M2 macrophages express the surface markers of CD163, CD86, and CD206 (MRC1, mannose receptor C-type 1), secrete cytokines including IL-10, TGF-β, and IL-6, and function in wound repair and tumor growth." (PMID 37749600, 2023). "IL-6 is overexpressed and secreted by the tumor microenvironment (TME), which comprises various cell types such as neutrophils, macrophages, monocytes, fibroblasts, endothelial cells, lymphocytes, and tumor cells." (PMID 36771154, 2023). "Luteolin has been demonstrated that it exerted significant tumor suppressive activity on several cancers, by suppressing the secretion of IL-6, IL-12 and TNF-α in macrophages." (PMID 37560476, 2023). "For example, L1CAM promoted STAT3 activation via the IL-6/IL-6Rα axis to regulate tumor angiogenesis and vessel stabilization." (PMID 37248458, 2023). "The underlying changes included increased DNA damage, upregulated IL-6 levels, and a regulated immune tumor microenvironment." (PMID 36672266, 2023). "Inflammation in CCA often leads to carcinogenesis with persistent IL6 secretion promoting tumor cell survival and growth." (PMID 36980644, 2023). "Hnrnpab is a gene encoding for a heterogeneous ribonucleoprotein that is highly expressed in tumor cells, and participates in several cancer-related pathways; such as G2/M checkpoints, DNA repair, and IL6/JAK/STAT3 signaling." (PMID 37583908, 2023).
tumor (continued). "IL-4, TGFβ and IL-8 were assessed in low amounts (471 to 820 pg/mg of tumor); CCL2, IL-12, IL-6 and IL-10 in moderate amounts (2825 to 3440 pg/mg of tumor); and IFNγ, TNFα, IL-1β and IL-2 in high amounts (6293 to 13,492 pg/mg of tumor)." (PMID 37526660, 2023). "The main mediators involved in promoting the PDT-induced acute-phase response of the tumor are glucocorticoid hormones and the cytokine IL-6." (PMID 37762219, 2023). "We further confirm IL-6 expression with the immune cells, the proportion of tumor-infiltrating immune subsets was analyzed using CIBERSORT algorithm, and 22 kinds of immune cell profiles in EOC samples were constructed." (PMID 37124547, 2023). "This tumor resistance was explained by the ability of IL-6 to induce the phosphorylation of tumor AKT, mTOR and NF-κB signaling." (PMID 37190141, 2023). "Microbiota‐mediated TLR5 signaling drives tumor expression of IL‐6, which promotes MDSC mobilization and accelerates tumor growth." (PMID 37937304, 2023). "CD36+CAF-derived MIF potentiated the capacity of MDSCs to promote immunosuppressive TME and tumor stemness via IL-6/STAT3 activation." (PMID 38065972, 2023). "IL-6 is a pleiotropic cytokine that is highly produced in tumor-bearing hosts and inhibits the antigen presentation ability of DCs by activating signal transducer and activator of transcription 3 (STAT3)." (PMID 37965271, 2023). "In both in vitro and in vivo generated TAMs, Fra-1 drives the differentiation toward the tumor-promoting M2d phenotype through mechanisms dependent on autocrine pathways triggered by the transactivation of the interleukin-6 promoter." (PMID 37176013, 2023). "Acknowledging the pivotal role played by the IL-6/STAT3 signaling pathway in tumor progression, efforts to hinder its hyperactivity have involved the exploration of therapeutic strategies such as IL-6 receptor mono-antibodies or STAT3 inhibitors." (PMID 37813837, 2023). "These two complementary signals lead to the activation of STA3 and NFkB transcription factors resulting in blocking IL‐12 secretion in favour of IL‐10 and IL‐6 release, such as described for tumour cells." (PMID 38117000, 2023). "IL6 secreted by tumor cells can activate STAT3 signaling, inducing HIF-1⍺ and VEGF and conditioning lymphatic endothelial cells to express CCL5." (PMID 37440925, 2023). "In our previous study, we revealed that deactivation of STING signaling in tumor cells increases p-STAT3 signaling, resulting in interleukin-6 (IL-6) and IL-1β production in the tumor microenvironment." (PMID 36622166, 2023). "Precisely, tumoral VEGF‐A up‐regulates BEST1 expression on monocytes through the MEK1/2‐ERK1/2‐ELK1 pathway, which improves secretion of cytokines IL‐6 and IL‐8, leading to the promotion of tumor cell proliferation." (PMID 37088729, 2023). "By tumor secretion of IL-6, for example, megakaryocytes are promoted, resulting in elevated platelet levels." (PMID 37190296, 2023). "After being stimulated by inflammatory mechanisms or tumor microenvironment, mesenchymal stem cells (MSCs) can secrete IL-6, initiating epithelial-mesenchymal transition (EMT), thereby further promoting the metastasis of LC cells." (PMID 37901456, 2023). "Tocilizumab has been proposed to support the anti-tumor effect of IFNα treatment in RCCs by inhibiting the IL-6-mediated expression of the suppressor of cytokine signaling 3 (SOCS3)." (PMID 37190141, 2023). "UVB irradiation-induced inflammatory responses accelerate skin damage through the secretion of proinflammatory cytokines, including IL-1β, IL-6, IL-8, and TNF-α38–40." (PMID 38102220, 2023). "Among the different inflammatory cytokines, IL-6 plays a primary role in the tumor-stroma cell crosstalk." (PMID 36639824, 2023). "This is performed by reducing tumor growth and inflammatory cytokine secretion (IL-6,-8, TNF-α), activating pro-apoptotic molecules, reducing glycolysis proteins, regulating impaired metabolism and immune responses, or preserving skeletal muscle mass." (PMID 36829437, 2023).
tumor (continued). "In this capacity, IL-6 can form a pool of highly tumorigenic cells capable of generating multiple cell types in a given tumor." (PMID 36900322, 2023). "IL-6 is essential for the growth, metastasis, and initiation of cancer; affecting tumor growth, differentiation, and the host immune defense mechanism." (PMID 38064478, 2023). "Taken together, our data identified ADH1B as a novel mesenchymal suppressor of tumor-promoting IL-6 overexpression." (PMID 37185128, 2023). "The correlation between blood inflammatory markers, including YKL-40 and IL-6, circulating tumor DNA, and tissue biomarkers of resistance to chemotherapy and outcome will be explored." (PMID 37328835, 2023). "In contrast, IL‐37 hinders tumor growth by promoting the polarization of TAMs from M2 to M1 by blocking IL‐6/STAT3 signaling." (PMID 38098217, 2023). "IL-6 has been shown to activate signaling pathways leading to tumor proliferation, the most studied of which are the JAK and STAT3 pathways." (PMID 37047012, 2023). "IL6 up-regulates Olfr29-ps1 expression in MDSCs, while Olfr29-ps1 is considerably reduced in MDSCs in B16 tumour mice after IL6 knockdown." (PMID 36817434, 2023). "Together with the reduction in the volume and weight of tumor, this plant extract increased the level of IL-2 in the bloodstream and reduced those of IL-6 during metastasis formation." (PMID 36768978, 2023). "In contrast, in hypoxic areas, the TME produces HIF, TGF-β, or IL-6, which provokes alternative (M2) activation of macrophages to promote tumor progression." (PMID 36816959, 2023). "In turn, the IL-6 secreted by activated fibroblasts enhanced tumor-cell proliferation and chemoresistance." (PMID 37173963, 2023). "The aggressive environment of metastatic PCa was mimicked by adding IL-6 to tumor spheres in this study." (PMID 37987305, 2023). "A deregulated IL-6 signaling pathway has been found to play an important role in tumor proliferation, migration, and adhesion." (PMID 37569777, 2023). "M2b macrophages also produce IL-6 in response to ICs or other stimuli that induces the activation of Th2 cells, inducing the activation of Th2 cells, which promote tumor progression." (PMID 37108657, 2023). "The proinflammatory cytokine interleukin 6 (IL-6) was overexpressed in OCCC with concurrent ARID1A deletion and PIK3CA mutation, and the cytokine promoted tumour cell growth and survival." (PMID 38275587, 2023). "IL-6 is one of these, a multifunctional molecule involved in regulating immune and inflammatory responses, and known to promote tumor growth and cancer cells invasion." (PMID 36990991, 2023). "IL-8, a proinflammatory chemokine, inhibits anti-tumor immune responses by inducing MDSCs in the tumor microenvironment and expanding the desmoplastic tumor stroma, similar to IL-6." (PMID 38026978, 2023). "RDW was proven to be associated with IL‐6, TNF‐α, hepcidin and other cytokines that can affect the biological behavior of tumor cells in previous study." (PMID 37143237, 2023). "The polarized microglial cells release high levels of O2 radicals to contribute to the genomic mutations and enhance the expression of IL-6 and TNF-α to support tumor survival." (PMID 37012233, 2023). "IL-6 is a well-characterized proinflammatory ligand that can initiate Jak-STAT signaling to promote tumor progression." (PMID 36849492, 2023). "The formation of beige adipocytes can be triggered by inflammatory mediators (such as interleukin-6 [IL-6]) and tumor-derived compounds (such as parathyroid hormone related protein [PTHrP])." (PMID 37205195, 2023). "Mechanistically, we also show that tumor cells are able to induce miR-214 production in stroma cells, following the activation of IL-6/STAT3 signaling, which is then released via EVs subsequently up-taken by cancer cells." (PMID 36639824, 2023). "The inflammatory cytokine IL-6 is critical to polarize M2 through the mTOR signaling complex 2 (mTORC2) and Akt, promoting tumor growth and metastasis." (PMID 38139779, 2023).